INS (insulin)
Diseases named in the same sentence as INS in open-access papers (continued):
Sharing a sentence is not in itself a finding about the gene and the disease.
Insulin resistance (continued). "Meta-analysis of randomized controlled trials confirmed superiority of telmisartan in improvement of insulin resistance, reduction of fasting blood glucose and blood insulin levels." (PMID 33776749, 2020). "Meanwhile, high levels of androgens promote the production of free fatty acids in PCOS patients, thus inhibiting insulin signal transduction and aggravating insulin resistance." (PMID 32256454, 2020). "This phenomenon occurred in the presence of increased circulating insulin levels, further demonstrating insulin resistance." (PMID 33208733, 2020). "Some studies suggest that TNF-α and IL-6 interact to interfere with insulin signal transduction, which leads to insulin resistance and eventually to the occurrence of GDM." (PMID 32280713, 2020). "The lack of effect after the first administration of 3 to AY mice is probably due to insufficient stimulation of the insulin release for overcoming insulin resistance in these mice." (PMID 33228030, 2020). "Nakatani found that the development of insulin resistance was closely related to ERS which promote the aggravation of insulin resistance and the insulin resistance of extrahepatic tissues." (PMID 32082187, 2020). "The key to the development of diabetes is insufficient insulin secretion and insulin resistance, and NPY is involved in these processes." (PMID 33123166, 2020). "Lower levels of IGF lead to increased insulin levels, abnormal glucose clearance, and insulin resistance." (PMID 32500016, 2020). "Clinical models for the diagnosis of NAFLD/NASH have been validated in prospective studies, however, several require measures such as waist circumference, homeostasis model assessment of insulin resistance, or fasting insulin or fasting glucose." (PMID 32841307, 2020). "Apart from endocrine and reproductive disorders, metabolic changes are often observed in PCOS patients: increased insulin concentration, insulin resistance (IR), and even type 2 diabetes." (PMID 32967289, 2020). "After confirming the insulin resistance state in cardiomyocytes, evidenced by impaired glucose uptake, as reported in different models, we aimed to evaluate the insulin-induced Akt activation in cardiomyocytes isolated from our MetS model." (PMID 31995605, 2020). "In another study Propolis supplementation with dose 100 and 300 mg/kg, for 8 weeks in male Wistar rats improved insulin resistance by decreasing insulin plasma levels." (PMID 32817750, 2020). "Triterpenoids act as insulin sensitisers, and p-polypeptides act as insulin-mimetic, which can increase cellular glucose uptake and decrease insulin resistance." (PMID 32190386, 2020). "As the mice age, they develop insulin resistance, increase their fasting insulin secretion and accumulate more fat mass, thus emphasizing their fasting glycemia." (PMID 32708537, 2020). "These positive effects of p38 MAPK are insulin-independent, and therefore can bypass insulin resistance." (PMID 32899870, 2020). "In the skeletal muscle, the Σn−3 FA content of cellular membranes plays a main role favoring the action of insulin; a high Σn−6/Σn−3 FA ratio would be deleterious to insulin sensitivity and ultimately would result in insulin resistance." (PMID 32429595, 2020). "DM is characterized by metabolic disorders that are related to defects in insulin secretion and/or insulin resistance, and it is characterized by chronic hyperglycemia." (PMID 32722679, 2020). "The impact of insulin and insulin resistance on the operation of various organs and pathways is captured in accordance with published research." (PMID 32155149, 2020). "Studies in animal models have shown that aerobic training improves insulin sensitivity as evidenced by a decrease in value of the homeostatic model assessment of insulin resistance (HOMA-IR) or Lee index in trained animals compared to the sedentary group." (PMID 33322719, 2020).
Insulin resistance (continued). "Reduction in insulin resistance parameters was accompanied by cellular evidence of improvement in insulin signaling and expression of genes involved in inflammation." (PMID 33292434, 2020). "Insulin resistance corresponds to the decreased ability of insulin to stimulate glucose uptake in muscle, adipose, and other tissue, and to inhibit hepatic gluconeogenesis." (PMID 33348802, 2020). "This is due to a larger quantity of fatty acids that can be released from peripheral fat stores and pre-existing insulin resistance related to obesity, which diminishes the insulin-induced inhibition of lipolysis." (PMID 33160364, 2020). "Femur BMAT, which is an insulin-sensitive tissue in healthy, normal-weight subjects, does develop insulin resistance in obesity and T2DM, similarly to other fat depots." (PMID 32311037, 2020). "This indicates that the insulin secretion in the model animals was relatively insufficient and insulin resistance was present." (PMID 32266256, 2020). "Insulin resistance, if left unchecked, leads to the exhaustion of the β-cell and a reduced insulin secretion, leading to hyperglycaemia and acute diabetes." (PMID 33299532, 2020). "On the other hand, TM6SF2 E167K has been reported to be associated with preserved insulin sensitivity, estimated by HOMA‐IR and adipose insulin resistance or measured by hyperinsulinaemic euglycaemic clamp." (PMID 33102799, 2020). "Other studies also found N-stearoyl-sphingosine (d18:1/18:0) (C18Cer) to be positively related to insulin resistance, and treatment to improve insulin sensitivity would reduce plasma level of C18Cer as well." (PMID 32252241, 2020). "At the cellular level, an accumulation of lipid moieties including ceramides, diacylglycerols, and long chain fatty acyl‐CoAs in insulin‐receptive skeletal muscle tissue characterizes insulin resistance." (PMID 32845565, 2020). "Impaired glucagon secretion after fatty meat suggests early pancreatic alpha-cell dysfunction, while higher insulin secretion after a carbohydrate meal is a compensatory mechanism for developing insulin resistance in obese subjects." (PMID 32411223, 2020). "Insulin sensitivity was assessed by homeostasis model assessment of insulin resistance (HOMA-IR) and hyperinsulinemic euglycemic clamp (M value)." (PMID 31832934, 2020). "Using multivariate logistic regression model, the associations between baseline obesity, lipid profiles and non-insulin-based insulin resistance indices with the incidence of prediabetes were analyzed." (PMID 33059672, 2020). "Under the condition of insulin resistance owing to increased homocysteine concentrations, cells in adipose tissues fail to respond to insulin effectively, which leads to disturbances in lipid metabolism." (PMID 32961936, 2020). "Increased adipose tissue lipolysis is a critical function of insulin resistance, as it leads to ectopic fat accumulation and further impairs insulin signalling in peripheral tissues." (PMID 32718202, 2020). "Insulin resistance (fasting insulin and HOMA‐index of insulin resistance) in early pregnancy was an important predictor for boys' sum of skinfolds, in addition to fasting glucose and maternal adiposity (leptin, BMI and neck circumference) throughout pregnancy." (PMID 32141687, 2020). "For example, isoorientin, a flavonoid found in PS, has proven to revert insulin resistance in adipocytes by stimulating the proper phosphorylation of proteins in the insulin signaling pathway." (PMID 32316129, 2020). "Insulin-sensitizing drugs that relieve insulin resistance and reduce its detrimental effects are frequently used in early stages of the disease." (PMID 32256145, 2020). "Ceramides are suggested to be independent antagonists to insulin signaling and induce insulin resistance." (PMID 32252241, 2020).
Insulin resistance (continued). "To achieve this goal, we studied the effect of in vivo shRNA-mediated GPAT gene silencing on bioactive lipid accumulation and the insulin signaling pathway in the gastrocnemius muscle of mice with diet-induced insulin resistance." (PMID 33036203, 2020). "The outcomes assessed included BMI and waist circumference, fasting serum insulin levels and insulin resistance as assessed by HOMA-IR, and androgenic status including serum total testosterone and sex hormone-binding globulin (SHBG) concentrations." (PMID 32442310, 2020). "Individuals in a pre-diabetic state compensate for insulin resistance by β-cells insulin hypersecretion, but as the disease progresses, β-cells progressively grow less able to supply the needed amount of insulin, gradually become exhausted, and eventually die." (PMID 31936158, 2020). "It is better to investigate the insulin level for calculating the Homeostatic Model Assessment of Insulin Resistance (HOMA) index, which we have considered in our future works." (PMID 32952581, 2020). "The basis of T2D is insulin resistance described as a weakened response of peripheral tissue to insulin, which in turn leads to impaired glucose homeostasis in the body." (PMID 33322719, 2020). "Myricitrin had a similar impact on insulin levels to vitamin E. Insulin resistance induced in the D-gal group (p<0.001)." (PMID 32821355, 2020). "The secreted cytokines TNFα and IL-6 cause insulin resistance in adipocytes through IKKβ and JNK1 kinase pathway activation, which interfere with insulin signaling via phosphorylation and subsequent IRS1 inactivation." (PMID 32878255, 2020). "Conversely, low serum amylase is associated with an increased risk/prevalence of metabolic syndrome and raised BMI, as well as insulin resistance and decreased insulin levels." (PMID 33294459, 2020). "Insulin resistance (IR) results from impaired glucose metabolism, and is characterized by a decreased sensitivity of target organs to insulin." (PMID 31679138, 2020). "Insulin resistance (IR) defined as an impaired biological response to insulin actions in the insulin-responsive tissues is considered central to the pathology of MetS." (PMID 32635565, 2020). "Elevated level of homocysteine leads to insulin resistance by increasing production of interleukin-6 (IL-6), a suppressor of insulin signaling and by inducing endoplasmic reticulum stress, a trigger of insulin resistance." (PMID 32365524, 2020). "Insulin resistance is characterized as reduced insulin sensitivity in the target tissue (like skeletal muscle, liver, and adipose)." (PMID 33150068, 2020). "One of the key metabolic deficits in T2D is peripheral insulin resistance, where the capacity of insulin to stimulate glucose uptake is impaired." (PMID 31396860, 2020). "Our findings suggest that, while glucose-mediated incretin release is followed by an increase in insulin release, the effect of the released insulin is limited through an increase in insulin resistance." (PMID 32385603, 2020). "Plasma insulin levels were also elevated in NICDiOE‐EC animals, indicating increased insulin resistance." (PMID 32187826, 2020). "ARTs such as protease inhibitors contribute to insulin resistance via a direct effect on insulin-mediated glucose transport leading to dysglycemia." (PMID 32645054, 2020). "In this mouse model, increased body fat correlates with whole body insulin resistance that manifests as hyperinsulinemia (i.e., elevated insulin levels in the blood), while reductions in body fat, correlate with improved insulin sensitivity." (PMID 32612981, 2020). "The role of ATP in the pathogenesis of insulin resistance is supported by the activities of metformin and chemical uncouplers, both of which improve insulin sensitivity in vivo." (PMID 32440681, 2020).
Insulin resistance (continued). "As ER stress has also been reported to play a crucial role in peripheral insulin resistance, impaired insulin secretion and the development of T2DM, ER-relevant gene and protein analyses were next investigated in the liver." (PMID 31396860, 2020). "In our study, A. squamosa inhibited the insulin glycation in vitro, suggesting its utility in helping to prevent glycation of functional and structural proteins in the progression of insulin resistance and diabetic complications." (PMID 33053901, 2020). "We also described the well-known enhancement of first-phase insulin secretion with insulin resistance and its reduction with fasting hyperglycemia." (PMID 33324238, 2020). "During the early stages of T2D, the pancreas increases insulin secretion to counteract insulin resistance." (PMID 33379327, 2020). "Insulin resistance and impaired insulin release were assessed by homeostasis model assessment (HOMA)." (PMID 32260174, 2020). "Insulin resistance refers to a decreased physiological response of peripheral tissues to insulin action, which implies an impaired effect of insulin in lowering the blood glucose." (PMID 32714368, 2020). "In summary, our findings indicate that metabolic abnormalities in terms of higher insulin levels and greater insulin resistance can be related to a history of ACEs in adult patients with schizophrenia spectrum disorders." (PMID 33255883, 2020). "Approximately 30−60% of cirrhotic patients exhibit metabolic impairment of blood glucose (hepatogenic diabetes) that reflects insulin resistance in the muscle, fat, and liver, as well as increasing secretion of insulin (hyperinsulinemia)." (PMID 33301501, 2020). "Elevated plasma-free fatty acids played a key role in the development of insulin resistance and T2D, and the decrease in plasma-free fatty acids was closely correlated with improvement in insulin sensitivity in T2D (r=0.76) subjects (P< 0.001)." (PMID 32982723, 2020). "In conclusion, both AP and PP diets similarly reduce oxidative stress markers MDA and protein carbonyls, but lead to an increase of the nitrosative stress marker NT in diabetic subjects, which were related to changes of fasting insulin and insulin resistance." (PMID 31926623, 2020). "One of the most important pathophysiological changes is the insulin target tissue (mainly liver, muscle) producing insulin resistance or accompanied by insufficient insulin secretion." (PMID 32964053, 2020). "In vitro studies have shown that exposure to high insulin (HI) alone results in insulin resistance in C2C12 skeletal muscle cells." (PMID 32230718, 2020). "Studies have focused on insulin resistance in the insulin-responsive tissues with less focus on other organs, such as the retina." (PMID 32432228, 2020). "McGarry suggested a vicious circle: increased steatosis levels results in insulin resistance, this in turn leads to even more steatosis all of which is triggered by an increase in lipogenesis in the insulin-resistant liver." (PMID 33776749, 2020). "This happens because the increase in BMI probably correlates with a greater insulin resistance that determines the need to increase the dose of insulin." (PMID 32215008, 2020). "T2D is typically preceded by insulin resistance; a condition in which the actions of insulin on peripheral tissues including skeletal muscle, liver, and adipose, are impaired." (PMID 33178196, 2020). "Higher insulin levels resulting from higher insulin resistance contribute to an increase in insulin-mediated ovarian testosterone production in thecal cells, further contributing to sex hormone imbalance." (PMID 33033953, 2020). "It has been described experimentally that plasma aminoadipic acid has a role in modulating glucose levels, being augmented as a compensatory response to hyperglycemia, probably by upregulating insulin secretion in early insulin resistance." (PMID 33082883, 2020).
Insulin resistance (continued). "We sought to test for peripheral insulin resistance via an insulin tolerance test (ITT), as insulin resistance is a known mechanism for increasing circulating and pancreatic insulin levels." (PMID 33113267, 2020). "Identical to T2DM, GDM also results because of insulin resistance and impaired pancreatic insulin secretion." (PMID 32174891, 2020). "In contrast, interleukin-6 was reduced, with both sources of choline compared to baseline, while eggs also had an effect on lowering C-reactive protein, insulin, and insulin resistance compared to baseline." (PMID 33066009, 2020). "The therapeutic value of insulin and the deleterious effect of insulin resistance on neuronal and glia cells, as it related to neurotrauma and neurodegeneration, has only recently been explored." (PMID 33100956, 2020). "As expected, serum insulin levels were greater than fivefold higher in HFD- than chow-fed mice (reflecting increased insulin resistance)." (PMID 32843711, 2020). "We found in this study that there was an increase in insulin resistance and a decrease in insulin sensitivity 30 min after TCC exercise." (PMID 32784834, 2020). "In the state of insulin resistance, insulin-mediated inhibition of adipocyte lipolysis and liver gluconeogenesis is weakened, resulting in increased plasma fatty acids and triglyceride synthesis in the liver." (PMID 32527258, 2020). "Insulin resistance (IR) is an abnormal condition in which the body responds to both endogenous and exogenous insulin." (PMID 32541513, 2020). "An increase of phosphorylation of IRS-1 at the residue ser307 (p-ser307IRS-1) hinders the insulin response and glucose utilization, thus viewed as the insulin resistance marker." (PMID 33267804, 2020). "IAPP is co-secreted with insulin, and in the course of insulin resistance-induced hyperinsulinemia, its secretion proportionally increases." (PMID 32397353, 2020). "Insulin resistance contributes to obesity and aging, and skeletal muscle insulin secretion resistance is involved in the pathogenesis of sarcopenia." (PMID 33198295, 2020). "In the ETRAL study, PI-controlled HIV-infected patients switched to a dual raltegravir-etravirine therapy gained fat and increased their insulin level, indicating increased insulin resistance." (PMID 31971958, 2020). "It is well known that beta‐cell secretion is dependent on insulin sensitivity such that in insulin resistance insulin secretion is increased." (PMID 32704562, 2020). "The compensatory rise in insulin levels (hyperinsulinemia) acts to exacerbate insulin resistance, thereby contributing significantly to the pathogenesis of the disease." (PMID 32230718, 2020). "Several studies showed that drugs that reduce inflammation, such as non-steroidal anti-inflammatory drugs (NSAIDs) are able to improve glucose-mediated insulin release, glucose tolerance, and reduce insulin resistance in diabetic patients." (PMID 33143088, 2020). "The physiologically increasing insulin resistance during pregnancy facilitates the supply of energy to the fetus and therefore insulin requirements rise continuously." (PMID 32374082, 2020). "Diet, exercise, and insulin sensitizers can increase adiponectin levels and reduce inflammation and insulin resistance through different mechanisms." (PMID 32685510, 2020). "Resistin is a member of cysteine-rich protein which appears to increase in T2D, obesity, and insulin resistance; resistin promotes insulin sensitivity through TNF-alfa and IL-6 activation." (PMID 32481506, 2020). "Insulin resistance (IR), which reflects insulin sensitivity, can be described as a decreased response of muscle and adipose tissues to the effects of insulin." (PMID 32454819, 2020). "A similar pattern of diminished insulin sensitivity and possible insulin resistance is therefore possible to develop in AL, particularly when compared to the leaner BI pig." (PMID 32326415, 2020).